ENPP1 (ectonucleotide pyrophosphatase/phosphodiesterase 1)
Diseases named in the same sentence as ENPP1 in open-access papers (continued):
Sharing a sentence is not in itself a finding about the gene and the disease.
hypophosphatemic rickets (28 papers, 2012 to 2025). Rickets due to low serum phosphate concentrations, the cause of which can be nutritional or genetic. "Inactivating mutations in the ENPP1 gene can cause bone mineralization defects and renal phosphate consumption, resulting in a rare autosomal recessive form of hypophosphatemic rickets (ARHR2)." (PMID 40270714, 2025). "We describe a rare case of ARHR2 with a bi-allelic ENPP1 pathogenic variant causing hypophosphatemic rickets." (PMID 35966073, 2022). "An ENPP1 Deficiency diagnosis should also be considered for children with evidence of hypophosphatemic rickets, joint, ligamentous, or arterial calcification/stenosis, or idiopathic hearing loss." (PMID 36150100, 2022). "These mice provide a new animal model for studies of otitis media and tympanosclerosis and for the hearing loss recently shown to be associated with human ENPP1 mutations causing generalized arterial calcification of infancy and hypophosphatemic rickets." (PMID 27959908, 2016). "Regardless, our findings in Enpp1−/− mice are consistent with human genetic studies that have recently shown that Enpp1, if mutated, causes hypophosphatemic rickets resulting from increased FGF-23 levels." (PMID 22359666, 2012). "Furthermore in some patients with generalised arterial calcification due to ENPP1 mutations in infancy, hypophosphatemic rickets developed in the following years." (PMID 30525344, 2019). "However, a phenotype of autosomal-recessive hypophosphatemic rickets without any arterial calcification was encountered in patients with mutations in the ENPP1 gene, suggesting a different pathway involved in the generation of hypophosphatemic rickets." (PMID 29976176, 2018). "Treatment of patients with ARHR2 is challenging due to its rarity and the fact that ENPP1 deficiency not only causes hypophosphatemic rickets but may also be associated with arterial, cardiac and/or articular calcification or may present as generalized arterial calcification in infancy." (PMID 35352187, 2022). "Osteocytes also express PHEX, DMP1, ENPP1, and FAM20C, and inactivating mutations cause FGF23-related hypophosphatemic rickets/osteomalacia." (PMID 36246908, 2022). "Mutations in four genes, FGF23 itself, PHEX, DMP1 and ENPP1, have been reported to remarkably increase the plasma levels of FGF23, leading to hereditary hypophosphatemic rickets." (PMID 22615579, 2012). "Various Enpp1 mutations have been identified in humans, but the phenotypes of patients carrying different Enpp1 mutations include OPLL, GACI and hypophosphatemic rickets, and different phenotypes occur with Enpp1 mutations in mice, which also include HO and impaired glucose tolerance." (PMID 39212714, 2024). "It is possible that the patient may develop the risk of hypophosphatemic rickets at a later stage, as many GACI patients with biallelic pathogenic variants in the ENPP1 gene progress to develop ARHR2." (PMID 39538190, 2024). "Specifically, some patients with ENPP1 variants develop hypophosphatemic rickets without a prior clinical history of GACI, while nearly all patients with ABCC6 variants present with PXE without a history of GACI." (PMID 35482848, 2022). "Autosomal-recessive forms of hypophosphatemic rickets (ARHR) may be caused by mutations in dentin matrix protein 1 (DMP1, as in ARHR1) or ectonucleotide pyrophosphatase/phosphodiesterase 1 (ENPP1, as in ARHR2)." (PMID 33815294, 2021). "The three forms of autosomal recessive hypophosphatemic rickets (ARHR) result from mutations in DMP1 [ARHR1,], ENPP1 [ARHR2,], and FAM20C [ARHR3,], while hypophosphatemic rickets and hyperparathyroidism (HRHPT) is caused by mutations that upregulate KLOTHO expression." (PMID 30808384, 2019).
hypophosphatemic rickets (continued). "Autosomal-recessive forms of hypophosphatemic rickets (ARHR1 and 2) are either caused by pathogenic variants in the dentine matrix acidic phosphoprotein 1 (DMP1) gene or in the ectonucleotide pyrophosphatase/phosphodiesterase 1 (ENPP1) gene, which are both expressed in bone and teeth." (PMID 34910242, 2022). "Ectonucleotide pyrophosphatase/phosphodiesterase 1 (ENPP1)-related multiple arterial stenoses is a rare clinical syndrome in which global arterial calcification begins in infancy, with a high probability of early mortality, and hypophosphatemic rickets develops later in childhood." (PMID 37153460, 2023).
type 2 diabetes (27 papers, 2007 to 2025). "Diseases associated with ENPP1 include Cole disease, autosomal recessive hypophosphatemic rickets, type 2 diabetes mellitus, HPP, and autism spectrum disorder." (PMID 41158885, 2025). "This region is within the intron of the Enpp1 gene, which encodes a pyrophosphatase, and has been shown to be related to type 2 diabetes." (PMID 27398095, 2016). "A risk haplotype of ENPP1 was associated with childhood obesity, glucose intolerance and type 2 diabetes." (PMID 25825681, 2015). "While several variants have been described over the years for all these genes, solid evidence of an association with type 2 diabetes and related diseases seems to exist only for rs1044498 of the ENPP1 gene and for rs2295490 of the TRIB3 gene." (PMID 23762820, 2013). "The strongest impact on type 2 diabetes when exclusively analysing the Danish data was found for the ENPP1 rs2021966 variant (OR = 1.15 95% CI 1.03–1.28, P = 0.015)." (PMID 21283750, 2011). "The ENPP1 QdelTG haplotype was associated with adult moderate and morbid obesity and type 2 diabetes and was also associated with increased serum levels of soluble ENPP1 protein in children." (PMID 22043164, 2011). "A meta-analysis of more than 40.000 individuals showed that ENPP1 K121Q increases risk of type 2 diabetes under a recessive model; an effect that may be modulated by BMI." (PMID 21283750, 2011). "In those studies we have suggested that lack of inclusion of this variable may contribute to the apparent discrepancy among published genetic association studies on ENPP1 K121Q and type 2 diabetes." (PMID 17849011, 2007). "Patients with type 2 diabetes mellitus display elevated levels of tyrosine phosphatase 1B (PTPN1), and membrane IR-associated glycoprotein PC-1 (ENPP1), which downregulate IR phosphorylation and insulin signal transduction." (PMID 39199273, 2024). "The functions of ENPP1 have been broadly studied in the fields of bone formation and type 2 diabetes." (PMID 29259245, 2017). "Furthermore, uric acid interferes with the insulin signaling pathway by attracting ectonucleotide pyrophosphatase/phosphodiesterase 1 (ENPP1) to the insulin receptor, thereby worsening the progression of type 2 diabetes." (PMID 41301787, 2025). "Furthermore, ENPP1 functions as an inhibitor in the insulin signaling pathway, modulating biological processes related to obesity and type 2 diabetes (T2D) by influencing insulin resistance (IR) in tissues and cells." (PMID 40282354, 2025). "For example, microarray studies performed on human pancreatic islets isolated from patients with type 2 diabetes and glucose-tolerant controls identified, among other changes, overexpression of ENPP1, TSPAN4, TSPAN8, CSRP1, REG3A and REG3G, genes that were also upregulated with age in our study." (PMID 26699651, 2016). "In contrast to that, both vascular calcification and increased bone mineral density are commonly observed in some patients with type 2 diabetes, a phenomenon that could not be explained by the increase of Enpp1 expression." (PMID 29513794, 2018).
autosomal recessive hypophosphatemic rickets (24 papers, 2011 to 2025). Autosomal recessive hypophosphatemic rickets (ARHR) is a hereditary renal phosphate-wasting disorder characterized by hypophosphatemia, rickets and/or osteomalacia and slow growth. "Genetic testing identified that the patient had an inactivating mutation in the ENPP1 gene, which is associated with Autosomal-Recessive Hypophosphatemic Rickets 2 (ARHR2)." (PMID 40270714, 2025). "After genetic testing was carried out, it was found that the patient had a monoallelic inactivation mutations in the ENPP1 gene, which is the pathogenic gene of Autosomal-Recessive Hypophosphatemic Rickets 2 (ARHR2)." (PMID 40270714, 2025). "In humans, ENPP1 mutation causes autosomal recessive hypophosphatemic rickets (ARHR) or generalized arterial calcification of infancy (GACI), in which ectopic calcification occurs in various tissues (e.g., aorta)." (PMID 35050204, 2022). "ENPP1 mutations cause autosomal recessive hypophosphatemic rickets (ARHR) or Generalized Arterial Calcification of Infancy (GACI) in humans." (PMID 28798354, 2017). "Mutations decreasing ENPP1 activity are associated with idiopathic infantile arterial calcification (GACI) as well as autosomal-recessive hypophosphatemic rickets." (PMID 21738662, 2011). "rhENPP1 ERT could also be a promising therapy for other diseases caused by loss-of-function mutations in ENPP1 or low plasma PPi levels, or characterized by ectopic vascular calcification, such as pseudoxanthoma elasticum, autosomal-recessive hypophosphatemic rickets and chronic kidney disease." (PMID 30158213, 2018). "Autosomal dominant hypophosphatemic rickets is due to FGF23 variants, while autosomal recessive hypophosphatemic rickets is due to biallelic variants in DMP1, ENPP1, FAM20C or SLC34A3." (PMID 40533633, 2025). "Autosomal Recessive Hypophosphatemic Rickets (ARHR) type 1 (MIM 241520) and 2 (MIM 613312) are associated with molecular defects in Dentin matrix protein 1 (DMP1) and the ectonucleotide pyrophosphatase phosphodiesterase 1 (ENPP1), respectively." (PMID 34068220, 2021). "Mutations in dentin matrix protein 1 (DMP1) and ectonucleotide pyrophosphatase/phosphodiesterase 1 (ENPP1) results in autosomal recessive hypophosphatemic rickets 1 and 2, respectively." (PMID 29515522, 2018). "Furthermore, several mutations in the ENPP1 gene result in the phenotype of autosomal recessive hypophosphatemic rickets (ARHR2) without any arterial calcifications." (PMID 30525344, 2019).
Pseudoxanthoma elasticum (24 papers, 2012 to 2026). "Recently it has become clear that the spectrum of human phenotypes that are caused by mutations in ENPP1 is variable, and less severe cases present themselves with symptoms of hypophosphatemic rickets or pseudoxanthoma elasticum (PXE; OMIM 264800)." (PMID 24906371, 2014). "For example, the ABBC6 gene is a member of the ATP-binding cassette transporter family, related to pseudoxanthoma elasticum (PXE), a pathology caused by a mutation in the ABCC6 and ENPP1 genes." (PMID 36982730, 2023). "In addition, ENPP1 mutations have been identified in some patients with pseudoxanthoma elasticum (PXE), another heritable ectopic mineralization disorder, although most cases with this disorder harbor mutations in the ABCC6 gene." (PMID 28402956, 2017). "The ENPP1 inactivation mutation has been identified as a potential defect in most of the cases of GACI, while mutations in ABCC6 are demonstrated in patients who are genotyped as pseudoxanthoma elasticum and only limited cases of GACI are reported." (PMID 38248755, 2023). "Mutations in ENPP1 have not been found in patients with pseudoxanthoma elasticum (PXE), another genetic multisystem ectopic calcification disorder caused by mutations in the ABCC6 gene." (PMID 35482848, 2022). "Furthermore, some cases of pseudoxanthoma elasticum (PXE) have recently been linked to ENPP1." (PMID 24906371, 2014). "Pseudoxanthoma elasticum (PXE) is driven primarily by biallelic ABCC6 variants, with overlapping ectopic-mineralization phenotypes from ENPP1 and GGCX." (PMID 41511357, 2026). "Pseudoxanthoma elasticum (PXE) is an ectopic calcification disorder caused by biallelic mutations in the ABCC6 (ATP-Binding Cassette, subfamily C member 6)–and in rare cases the ENPP1 (Ectonucleotide Pyrophosphatase/Phosphodiesterase 1)–gene." (PMID 35317004, 2022). "Pseudoxanthoma elasticum (PXE; OMIM# 264800) is an autosomal recessive metabolic disease caused by loss-of-function pathogenic variants in the ABCC6 (ATP-binding cassette, subfamily C, member 6) gene and—to a much lesser extent—the ENPP1 (ectonucleotide pyrophosphatase/phosphodiesterase 1) gene." (PMID 38002303, 2023). "In addition to ARHR2 and GACI, loss-of-function pathogenic variants in ENPP1 can lead to progressive mixed hearing loss, ossification of the posterior longitudinal ligament, pseudoxanthoma elasticum (PXE), thrombocytopaenia, hypoglycaemia, neurologic and hepatic manifestations." (PMID 41445557, 2025).
diabetes (20 papers, 2011 to 2025). "It has been shown that the K121Q polymorphism in the ENPP1 gene is a risk factor for diabetes mellitus (DM) and diabetic kidney disease, but its association with AR has not been evaluated." (PMID 31318911, 2019). "Both Enpp3 and Enpp1 have both been associated with diabetes." (PMID 23826075, 2013). "(iv) Finally, an important function attributed to ENPP1 is the inhibition of the insulin receptor tyrosine kinase, which has a role in the insulin resistance of non-insulin-dependent diabetes mellitus." (PMID 39641818, 2024). "In the subset of individuals who had a second liver biopsy, only those that had remission of diabetes and improvement in insulin sensitivity had an increase in liver ENPP1 protein abundance." (PMID 25539584, 2014). "The ENPP1 Lys121Gln gain-of-function polymorphism enhances the interaction between the ENPP1 glycoprotein and insulin receptor (INSR), contrasting INSR kinase activity, and is associated with an increased diabetes risk." (PMID 23394097, 2013). "If we assume that this insulin-regulated ENPP1 expression exists in cells responsible for bone health, we probably can come up with a hypothesis to explain part of the bone health problems in patients with diabetes." (PMID 29513794, 2018). "In this study, our primary aim was to examine ENPP1 levels in liver tissue taken at RYGB surgery and later after remission of diabetes." (PMID 25539584, 2014). "To control for the effect of treatment on ENPP1 levels, we performed ANOVA analysis to test whether different treatments for diabetes affected ENPP1 levels." (PMID 25539584, 2014). "We hypothesized that liver ENPP1 levels would be higher in individuals with T2DM and would decrease after remission of diabetes." (PMID 25539584, 2014). "(vi) Finally, there is circumstantial evidence that Enpp3 may be also related to diabetes, though a direct link to the insulin receptor, as that known to occur in the case of ENPP1, has not been reported." (PMID 39641818, 2024). "However, ENPP1 mRNA expression did not change significantly after remission of diabetes, even though individuals with T2DM had lower expression than those with normal glucose tolerance at RYGB surgery." (PMID 25539584, 2014).
rickets (18 papers, 2011 to 2025). Bone softening and weakening usually caused by deficiency or impaired metabolism of vitamin D. Deficiency of calcium, magnesium, or phosphorus may also cause rickets. "We estimated that 70% of individuals with ENPP1 Deficiency who survive to age 10 will have developed musculoskeletal complications, primarily rickets and/or osteomalacia." (PMID 40176950, 2025). "But in contrast to the ABCC6 mutations, the incidence of ENPP1 mutations was higher in terms of mortality, rickets, joint calcification, hearing complications, and neurological complications." (PMID 38165475, 2024). "Targeted gene panel sequencing was performed to investigate the genetic cause of rickets, and a homozygous nonsense variant in ENPP1, c.783C>G (p.Tyr261*), was identified." (PMID 35966073, 2022). "Further genetic analysis via next-generation sequencing (NGS) was conducted using a panel of 21 genes associated with rickets or calcium/phosphate metabolism disorders (including ENPP1, FAM20C, SLC34A3, and VDR)." (PMID 35966073, 2022). "An interesting report about hypophosphatemic rickets in an OPLL patient due to a homozygous mutation in the ENPP1 gene, substantiates the likely importance of this gene in the etiopathogenic mechanism of OSL." (PMID 36276944, 2022). "Our studies demonstrate that in addition to GACI and rickets, ENPP1-deficiency can also present as classical PXE, a finding that extends the clinical spectrum of ENPP1-associated diseases." (PMID 35482848, 2022). "Of the ENPP1‐deficient affected individuals that survived the initial critical period, 70% reported signs of rickets." (PMID 34355424, 2021). "Clinical signs of rickets were reported in 40 of 127 affected individuals (36.7%) in the full data set; this prevalence was higher in affected individuals with ENPP1 variants (36/38 [48.6%]) than in those with ABCC6 variants (3/18 [16.7%])." (PMID 34355424, 2021). "Of the 50 surviving affected individuals with ENPP1 variants, 34 of 48 assessed (70.1%) developed rickets." (PMID 34355424, 2021). "It is not clear why there is an overlapping GACI phenotype (arterial calcification with cardiovascular complications) between ENPP1 and ABCC6 deficiencies but a difference in the eventual development of rickets with ENPP1 variants." (PMID 34355424, 2021). "However, a prospective evaluation of 16 ENPP1-deficient patients who survived past infancy found progressive hearing loss and a 100% probability of the development of rickets by the age of 14 years." (PMID 35895733, 2022). "The later onset of low bone mass and osteoporosis juxtaposed to biallelic ENPP1 Deficiency with clinically‐apparent rickets during childhood provides an intriguing possibility of a gene dosage effect in the presentation of skeletal complications of ENPP1 Deficiency." (PMID 36150100, 2022). "A periodic systematic evaluation is needed to identify any comorbidities in ARHR2 patients since ENPP1 variants may present phenotypes other than rickets and symptoms may evolve or change over time." (PMID 35966073, 2022). "Since rickets related to ENPP1 deficiency is also mediated by FGF23, the use of burosumab has been proposed as a therapeutic strategy in ARHR2 patients." (PMID 37871131, 2024). "Despite the similar calcification phenotype between ENPP1 and ABCC6 deficiencies, there was a disparity in the mortality rate and the presence of rickets in the ENPP1 versus ABCC6 cohorts." (PMID 34355424, 2021). "Clinical signs of rickets are seen in 49% of individuals with ENPP1 deficiency regardless of age or survival status and in 70.1% of patients who survive the critical period." (PMID 37871131, 2024). "The vascular status of an ENPP1-mutated patient when they enter the rickets phase has not been thoroughly explored." (PMID 37153460, 2023).